ETFA (electron transfer flavoprotein subunit alpha)
Description:
Heterodimeric electron transfer flavoprotein that accepts electrons from several mitochondrial dehydrogenases, including acyl-CoA dehydrogenases, glutaryl-CoA and sarcosine dehydrogenase. It transfers the electrons to the main mitochondrial respiratory chain via ETF-ubiquinone oxidoreductase (ETF dehydrogenase). Required for normal mitochondrial fatty acid oxidation and normal amino acid metabolism.
Synonyms: GA2; EMA; MADD
Tractability: Small molecule: a structure with a bound ligand is known. PROTAC: ubiquitination databases record sites on it; its protein half-life has been measured.
Gene: Protein-coding gene on chromosome 15 (76,188,555 to 76,311,730, reverse strand). Ensembl gene ENSG00000140374.
Subcellular location: Mitochondrion matrix
Subcellular location (Human Protein Atlas): Mitochondria
Pathways (Reactome):
Metabolism: Respiratory electron transport
Gene Ontology:
Molecular function: electron transfer activity; flavin adenine dinucleotide binding; protein binding
Biological process: amino acid catabolic process; fatty acid beta-oxidation using acyl-CoA dehydrogenase; respiratory electron transport chain
Cellular component: electron transfer flavoprotein complex; mitochondrial matrix; mitochondrion
Genetic constraint (gnomAD): Loss-of-function variants: 10 observed, 14.54 expected, observed/expected ratio (o/e) 0.69, 90% interval 0.42 to 1.17. The upper end of that interval is the gene's LOEUF score, 1.17, which puts it in group 5 of 6, group 1 being the genes least tolerant of losing a copy. Missense variants: 178 observed, 209.58 expected, observed/expected ratio (o/e) 0.85, 90% interval 0.75 to 0.96. Synonymous variants: 82 observed, 77.24 expected, observed/expected ratio (o/e) 1.06, 90% interval 0.89 to 1.28.
Gene-disease validity (ClinGen):
ClinGen rates the evidence that ETFA causes each of these diseases.
multiple acyl-CoA dehydrogenase deficiency (autosomal recessive): Definitive.
Homologues: Orthologues: chimpanzee ETFA (99% identical), mouse Etfa (96% identical), macaque ETFA (95% identical), rat Etfa (95% identical), dog ETFA (94% identical), guinea pig ETFA (93% identical), pig ETFA (93% identical), rabbit ETFA (92% identical), zebrafish etfa (80% identical), tropical clawed frog etfa (69% identical).
Diseases named in the same sentence as ETFA in open-access papers:
ETFA is named in the same sentence as 47 diseases in open-access papers, as found by Europe PMC text mining. Sharing a sentence is not in itself a finding about the gene and the disease. The quoted sentences say what the papers report.
multiple acyl-CoA dehydrogenase deficiency (24 papers, 2017 to 2025). "One of these disorders, MADD or glutaric aciduria type II is usually caused by biallelic pathogenic variants in the gene ETFDH encoding ETF-CQ or genes encoding electron-transfer flavoproteins (ETFA, ETFB)." (PMID 39586906, 2024). "Multiple acyl‐CoA dehydrogenase deficiency due to mutation in ETFA can cause muscle weakness and weight loss." (PMID 30977266, 2019). "Mutations in ETFA cause multiple acyl-CoA dehydrogenase deficiency (MADD), however metabolic screening in the patient revealed no MADD-typical pattern and lipid accumulation was also absent in muscle excluding this diagnosis." (PMID 29361167, 2018). "Glutaric acidemia type-II, caused by mutations of either ETFA, ETFB or ETFDH that collectively encode the OXPHOS enzyme electron transfer flavoprotein, is also characterized by PKD." (PMID 28205547, 2017). "Multiple acyl-CoA dehydrogenase deficiency (MADD) also known as glutaric academia type II or lipid-storage myopathy—is caused by loss-of-function variants in ETFDH, ETFA, ETFB or, more rarely, FLAD1." (PMID 40963932, 2025). "The multiple acyl-CoA dehydrogenase deficiency (MADD), also called GAII, is caused by genetic defects in the electron transfer flavoprotein ETF and its dehydrogenase ETFDH, which are encoded by ETFA, ETFB, and ETFDH, respectively." (PMID 40225143, 2023). "The variants of electron transfer flavoprotein (ETFA, ETFB) and ETF dehydrogenase (ETFDH) are the leading cause of glutaric aciduria type II (GA-II)." (PMID 34573316, 2021). "Mutations in ETFA cause glutaric acidemia IIA, 1 form of multiple acyl‐CoA dehydrogenase deficiency." (PMID 30977266, 2019). "In multiple acyl-CoA dehydrogenase deficiency (MADD), mutations in ETFa, ETFb, or ETFDH, lead to decreased ATP production with an accumulation of organic acids, including glutaric acid as well as acyl-carnitines." (PMID 32038305, 2019). "A prime example is multiple acyl-CoA dehydrogenase deficiency (MADD), caused by mutations in ETFDH, ETFA, or ETFB genes encoding electron transfer flavoprotein or its dehydrogenase." (PMID 40963932, 2025).
glioma (4 papers, 2015 to 2019). A benign or malignant brain and spinal cord tumor that arises from glial cells (astrocytes, oligodendrocytes, ependymal cells). "Third, variants in CCDC26 (the 8q24 locus), C2orf80 (close to IDH), LRIG1, PHLDB1, ETFA, MAML2 and ZBTB16 were associated with IDH-mutant glioma." (PMID 31842352, 2019). "Furthermore, we observed a significant association between the genetic variants in LRIG1, PHLDB1, ETFA, ZBTB16 and MAML2 and the risk of IDH-mutant glioma." (PMID 31842352, 2019). "Risk variants in LRIG1, PHLDB1, ETFA, MAML2 and ZBTB16 were also associated with IDH-mutant glioma." (PMID 31842352, 2019). "Furthermore, the gene encoding electron transfer flavoprotein α subunit (ETFA), which also interacts with IDH proteins, also comprises a glioma susceptibility locus." (PMID 29317492, 2018). "Collectively POLR3B, ETFA, VTI1A, ZBTB16 and PHLDA1 are altered in 8% (22/286) of LGG as compared with 3% (8/273) of GBM (P=0.014) providing support for these genes having a role in glioma tumorigenesis." (PMID 26424050, 2015). "MAML2 and ETFA are currently not established to have a clear role in somatic alterations in glioma." (PMID 31842352, 2019).
Hyperammonemia (3 papers, 2019 to 2023). An increased concentration of ammonia in the blood. "Thus, the R115X mutation by itself is unlikely to be a major contributor to hyperammonemia, but could enhance the effect of the deleterious ETFA mutation, because both genes participate in fatty acid oxidation." (PMID 30977266, 2019). "The metabolic decompensation may be life-threatening with encephalopathy and hyperammonemia, and neither clinical symptoms nor biochemical findings allow distinguishing RFVT1 deficiency from MADD deficiency (caused by biallelic ETFA, ETFB and ETFDH variants)." (PMID 37510312, 2023).
Alzheimer disease (1 paper, 2023). A progressive, neurodegenerative disease characterized by loss of function and death of nerve cells in several areas of the brain leading to loss of cognitive function such as memory and language. "Furthermore, ETFA expression has been observed to change in an Alzheimer’s disease mouse model in response to aducanumab, an amyloid beta antibody." (PMID 36525587, 2023).
Gliosis (1 paper, 2015). Gliosis is the focal proliferation of glial cells in the central nervous system. "Mutations of ETFA have been reported to be a cause of recessive glutaric acidaemia IIA (refs 28, 29), which features gliosis." (PMID 26424050, 2015).
Headache (1 paper, 2025). Cephalgia, or pain sensed in various parts of the head, not confined to the area of distribution of any nerve. "The gene set for headache (ETFA, GRHPR, MMAB) was enriched in two primary functional clusters: one centered on core mitochondrial energy pathways, including ‘oxoacid metabolism’; and another related to molecular binding functions, such as ‘nucleoside phosphate binding’." (PMID 40943610, 2025). "Similarly, genes identified for headache (e.g., ETFA, GRHPR, MMAB) and facial pain (e.g., FASN, SPHK2) also consistently showed protective trends at both the expression and protein levels." (PMID 40943610, 2025).
Hypercholesterolemia (1 paper, 2022). An increased concentration of cholesterol in the blood. "To mimic the milder downregulation of ETFα induced by hypercholesterolemia but not severely demolished like MADD, we use morpholino to knockdown ETFA in zebrafish embryos to leave residual ETFA function." (PMID 35313640, 2022).
leukemia (1 paper, 2022). A malignant (clonal) hematologic disorder, involving hematopoietic stem cells and characterized by the presence of primitive or atypical myeloid or lymphoid cells in the bone marrow and the blood. "As AML is the second most common childhood leukemia, we utilized the TARGET pediatric study to analyze ETFA and ETFB expression and again found down-regulation or no significant change of ETFA and ETFB in most subtypes of AML." (PMID 35177813, 2022).
Obesity (1 paper, 2011). Accumulation of substantial excess body fat. "Our data showed that ATP synthase D chain, ubiquinol cytochrome-C reductase core protein 1 and electron transfer flavoprotein subunit alpha peptide levels were altered with obesity." (PMID 20859605, 2011).
organic acidemias (1 paper, 2021). "With the suspicion of organic acidemias early in her life, the coding regions and splicing sites of GCDH, ETFA, ETFB, ETFDH, IVD were evaluated by PCR and sequencing and no pathogenic variant was identified." (PMID 35083005, 2021).
polycystic kidney disease (1 paper, 2024). A usually autosomal dominant and less frequently autosomal recessive genetic disorder characterized by the presence of numerous cysts in the kidneys leading to end-stage renal failure. "In fetuses with isolated renal anomalies, the highest detection rate of pathogenic variants was among fetuses with isolated polycystic kidney disease (29% PKHD1, PKHD1, PKD1, ETFA)." (PMID 37535131, 2024).
Respiratory insufficiency (1 paper, 2014). "Interestingly, patients with respiratory insufficiency have lower levels of TNNT3, MDH2, and ETFA than the ones without, suggesting that patient sub-groups within the DMD cohort could be identified." (PMID 24920607, 2014).
cancer (3 papers, 2019 to 2025). A tumor composed of atypical neoplastic, often pleomorphic cells that invade other tissues. "Targeting these interactions, such as integrin β1 or ETFA blockade, offers promising strategies for cancer treatment." (PMID 40806736, 2025).
metabolic disorders (3 papers, 2018 to 2025). "Our study increased the range of ETFA gene variants, provided a better understanding of ETFA variants on phenotypic outcome and reinforced the clinical importance of this gene in patients with neonatal-onset metabolic disorders." (PMID 41254678, 2025). "No additional genetic variants associated with metabolic disorders that cause increased C8 levels, such as mutations in the ETFA, ETFB, and ETFDH genes, were identified through high-throughput sequencing, leading to a final diagnosis of MCADD." (PMID 41002789, 2025). "During subsequent follow-up, consistently elevated levels of C8 and C8/C10 were observed, and high-throughput sequencing did not reveal any additional genetic metabolic disorders associated with elevated C8 (including variations in the ETFA, ETFB, and ETFDH genes)." (PMID 41002789, 2025).
tumor (3 papers, 2022). "Steady-state levels of CPT1, the electron transfer flavoprotein subunit α (ETFA) and HADHA, three proteins involved in the mitochondrial transport and oxidation of FA, increased significantly in tumor biopsies." (PMID 35534478, 2022).
myopathy (1 paper, 2014). A disease of the muscle in which the muscle fibers do not function properly. "In patients with muscular symptoms and histologically proven lipid storage myopathy but unremarkable metabolite patterns molecular analysis (starting with the ETFDH gene, followed by sequencing of ETFA and ETFB) is advisable." (PMID 25200064, 2014).
ETFA also shares sentences with these, for which no sentence is quoted: infection (4 papers); Sandhoff disease (4); Tay-Sachs disease (4); Fabry disease (3); genetic disorder (3); GM2 gangliosidosis (3); autosomal recessive disease (2); colorectal cancer (2); glutaric acidemia IIA (2); Insulin resistance (2); lipid storage myopathies (2); Aortic dissection (1); asthma (1); astrocytoma (1); bacterial infections (1); brain malformations (1); breast carcinoma (1); cardiomyopathy (1); cognitive decline (1); coronary heart disease (1); delirium (1); Encephalopathy (1); gastric cancer (1); glioblastoma (1); malaria (1); melanoma (1); muscular dystrophy (1); ophthalmoplegia (1); phospholipidosis (1); thoracic aortic aneurysm (1).
A further 1 disease shares a sentence with ETFA in 1 paper.